PPBP (pro-platelet basic protein)
Diseases named in the same sentence as PPBP in open-access papers (continued):
Sharing a sentence is not in itself a finding about the gene and the disease.
atrial fibrillation (3 papers, 2022 to 2025). A disorder characterized by an electrocardiographic finding of a supraventricular arrhythmia characterized by the replacement of consistent P waves by rapid oscillations or fibrillatory waves that vary in size, shape and timing and are accompanied by an irregular ventricular response. "Some studies have pointed out that CXCL7/PPBP and CXCL1 are the hub genes with the most associations in atrial fibrillation." (PMID 40078458, 2025). "In addition, CXCL7/PPBP and CXCL1 are the hub gene in atrial fibrillation with the highest number of associations." (PMID 36613652, 2022). "In humans, an important role in atrial fibrillation may be played by CXCL7/pro-platelet basic protein (PPBP), a ligand of CXCR2." (PMID 36613652, 2022).
depression (3 papers, 2018 to 2024). "Higher levels of PF4 and PPBP expression have also been observed in the blood of patients with depression." (PMID 38271077, 2024).
invasive breast carcinoma (3 papers, 2020 to 2023). A carcinoma that infiltrates the breast parenchyma. "This was observed for CXCL1 and CXCL6 in breast invasive carcinoma, PPBP in kidney chromophobe, CXCL3 in kidney renal papillary cell carcinoma, CXCL6 in pancreatic adenocarcinoma, CXCL6 in thyroid carcinoma, and CXCL3 in thymoma." (PMID 37686093, 2023). "As shown in, PPBP and RAB9A, show a significant change in gene expression in DCIS but no change in gene expression in invasive breast cancer tissue from human clinical samples." (PMID 32051475, 2020).
thyroid carcinoma (3 papers, 2021 to 2023). "For instance, we failed to explore the role of the 5 feature genes (BMP8A, ADARB2, SALL3, PPBP, and SCN1A) in onset and progression of thyroid carcinoma by molecular experiments, cell experiments, or animal experiments." (PMID 34697553, 2021).
acute leukemia (2 papers, 2014 to 2024). A clonal (malignant) hematopoietic disorder with an acute onset, affecting the bone marrow and the peripheral blood. "Our combination of gene expression profiling with a computational approach using STRING showed PPBP to be a hub gene in ALL, as has been observed in AML, and based on its important role in biological processes, PPBP could be considered a potential drug target in acute leukemias." (PMID 38339034, 2024).
acute myeloid leukemia (2 papers, 2022 to 2023). Acute myeloid leukemia (AML) is a group of neoplasms arising from precursor cells committed to the myeloid cell-line differentiation. "Here, cases such as the platelet basic protein (PPBP) in acute myeloid leukemia, which was previously identified as a dysregulated hub gene, can be highlighted." (PMID 37835457, 2023).
chronic hepatitis C (2 papers, 2022 to 2023). "To verify the results of the trial study, we examined the levels of the 9 proteins, IGHV, GAPDH, C1s, GRP78, V-ATPase, PPBP, CD9, Lp(a) and SAP, in EVs isolated from the sera of another 80 patients with chronic hepatitis C before DAA treatment." (PMID 35797333, 2022). "In patients with colorectal polyps without liver disease, serum SAP and PPBP levels were both significantly higher than those in patients with chronic hepatitis C (p = 7.1E-10, 8.7E-7, respectively." (PMID 35797333, 2022). "Serum SAP and PPBP levels in patients with chronic hepatitis C before DAA treatment could be measured by ELISAs and were highly positively correlated with the EV SAP and PPBP levels measured by targeted proteomics." (PMID 35797333, 2022).
lung disease (2 papers, 2021 to 2023). "PBPP/CXCL7 has been shown to be essential for neutrophil migration into the thrombus, and the formation of platelet–neutrophil aggregates and murine models of acute lung injury showed that deletion of PPBP/CXLC7 protected the mice from lung disease, as well as blocking platelet activation." (PMID 34273008, 2021).
melanoma (2 papers, 2013 to 2024). A malignant, usually aggressive tumor composed of atypical, neoplastic melanocytes. "For instance, S100B, C reactive protein (CRP), lactate dehydrogenase (LDH), pro-platelet basic protein precursor PPBP and IL-8 may help to determine the prognosis of melanoma patients." (PMID 23533572, 2013).
Obesity (2 papers, 2018 to 2022). Accumulation of substantial excess body fat. "Indeed, we observed that complement activation was an obesity-enriched gene set in CMS4 tumors and that the platelet marker PPBP was found to be an obesity-linked hub gene in CMS4 tumors." (PMID 35560039, 2022).
psoriasis (2 papers, 2019 to 2022). An autoimmune condition characterized by red, well-delineated plaques with silvery scales that are usually on the extensor surfaces and scalp. "PPBP has been found to be important for regulating excessive inflammation in psoriasis." (PMID 36699197, 2022).
thrombosis (2 papers, 2021 to 2023). "CXCL7 (PPBP) plays a prominent role in recruiting neutrophils to the injury site during thrombosis." (PMID 37355563, 2023).
thymoma (2 papers, 2015 to 2023). A neoplasm arising from the epithelial cells of the thymus. "In MG patients with versus without thymoma, 58 lncRNAs had 271 ‘cis’ genes upstream or downstream of their chromosomal position: lncRNA oebiotech_22652 had the highest number of ‘cis’ genes, whereas lncRNA oebiotech_12244 had 6 ‘cis’ genes(PPBP, CXCL1, CXCL5, PF4V1, PF4, and C14orf45)." (PMID 25889429, 2015).
aneurysm (1 paper, 2022). Bulging or ballooning in an area of an artery secondary to arterial wall weakening. "Among them, six hub genes might be the core genes for the rupture of aneurysms, including APP, JUN, GSK3B,ErbB2, PPBP and THBS1." (PMID 35432454, 2022).
cervical squamous cell carcinoma (1 paper, 2023). A squamous cell carcinoma arising from the cervical epithelium. "In another example, cervical squamous cell carcinoma and endocervical adenocarcinoma exhibited a negative correlation between the expression of CXCL1, CXCL6, and CXCL8 and EMT, whereas the expression of CXCL3, CXCL5, and PPBP positively correlated with EMT." (PMID 37686093, 2023).
Chagas disease (1 paper, 2023). A parasitic infection caused by Trypanosoma cruzi. "Levels of pro-platelet basic protein (PPBP) and other peripheral blood mononuclear cells correlate with disease state in Chagas disease." (PMID 36936778, 2023).
chronic hepatitis B (1 paper, 2022). "Next, we also measured serum SAP and PPBP levels in patients with colorectal polyps without liver disease as a control group and in patients with chronic hepatitis B and nonalcoholic fatty liver disease (NAFLD) as a group of patients with other liver diseases." (PMID 35797333, 2022).
Cirrhosis (1 paper, 2019). A chronic disorder of the liver in which liver tissue becomes scarred and is partially replaced by regenerative nodules and fibrotic tissue resulting in loss of liver function. "The results revealed the significant diagnostic values of PF4 and PPBP in cirrhotic HCC, and CCL19, CCL25 in non-cirrhotic HCC, while no significant diagnostic values of CNR1 in HCC with or without cirrhosis were found." (PMID 31346321, 2019).
colon adenocarcinoma (1 paper, 2023). "In colon adenocarcinoma, CXCL1, CXCL2, and CXCL3 negatively correlated with EMT, while CXCL5, CXCL6, PPBP, and CXCL8 positively correlated with EMT." (PMID 37686093, 2023). "For example, in colon adenocarcinoma, the expression of CXCL1, CXCL2, and CXCL3 negatively correlated with EMT, whereas the expression levels of CXCL5, CXCL6, PPBP, and CXCL8 positively correlated with EMT." (PMID 37686093, 2023).
esophageal carcinoma (1 paper, 2023). A primary or metastatic malignant neoplasm involving the esophagus. "Similar correlations were observed in esophageal carcinoma, with CXCL1, CXCL2, CXCL3, and PPBP negatively correlated with EMT, CXCL5 and CXCL6 positively correlated with EMT, and CXCL8 not correlated with EMT." (PMID 37686093, 2023).
fibrosis (1 paper, 2022). the formation of excess fibrous connective tissue in an organ or tissue in a reparative or reactive process. "Although the AUCs did not significantly increase for combination of SAP with PPBP compared to SAP or PPBP alone (data not shown), both SAP and PPBP had significantly higher AUCs than the FIB-4 index, especially in diagnosing patients with stage F4 fibrosis." (PMID 35797333, 2022).
heroin addicts (1 paper, 2021). "For example, major platelet-derived immune molecules, including the chemokine PF4 and PPBP, were significantly increased at the transcription level in AW heroin addicts." (PMID 34489980, 2021).
ischemia (1 paper, 2019). A hypoperfusion of the BLOOD through an organ or tissue caused by a PATHOLOGIC CONSTRICTION or obstruction of its BLOOD VESSELS, or an absence of BLOOD CIRCULATION. "Pro-platelet basic protein (PPBP) can be released in large amounts from activated platelets, and is a key participant in both homeostasis and inflammation during ischemia." (PMID 31262327, 2019).
Parkinson disease (1 paper, 2022). A progressive degenerative disorder of the central nervous system characterized by loss of dopamine producing neurons in the substantia nigra and the presence of Lewy bodies in the substantia nigra and locus coeruleus. "Nonetheless, all the evidence suggests that PROS1, PPBP, and LCN2 are known to be well detectable in vivo in blood and thus represents a potentially valuable source of biomarkers for Parkinson’s diseases." (PMID 36189230, 2022). "Receiver operating characteristic (ROC) of PPBP, PROS1, and LCN2 for prediction of Parkinson’s disease and healthy controls." (PMID 36189230, 2022).
periodontitis (1 paper, 2024). An acute or chronic inflammatory process that affects the tissues that surround and support the teeth. "In this study, seven genes (CD19, CXCR4, FABP4, FOS, IGHD, IL2RG, and PPBP) were significantly up-regulated in periodontitis samples." (PMID 39917706, 2024). "A total of 7 genes (CD19, CXCR4, FABP4, FOS, IGHD, IL2RG, and PPBP) were upregulated in periodontitis samples." (PMID 39917706, 2024).
pleural tumor (1 paper, 2018). "Our experiments using CXCR1- and CXCR2-deficient mice support that pleural tumor cell-secreted CXCL1/PPBP is cardinal for MPE and are in line with a previous study demonstrating increased production of CXCL1 by tumor cells during human MPE development that mobilizes regulatory T cells." (PMID 29445180, 2018).
rectal cancer (1 paper, 2026). A primary or metastatic malignant neoplasm that affects the rectum. "While PPBP’s involvement in platelet activation hints at its potential relevance, its specific predictive value in rectal cancer is less established." (PMID 41550766, 2026).
rectum adenocarcinoma (1 paper, 2023). An adenocarcinoma arising from the rectum. "In rectum adenocarcinoma, CXCL1 and CXCL3 negatively correlated with EMT, while CXCL5, CXCL6, PPBP, and CXCL8 were positively correlated." (PMID 37686093, 2023).
teratoma (1 paper, 2021). A non-seminomatous germ cell tumor characterized by the presence of various tissues which correspond to the different germinal layers (endoderm, mesoderm, and ectoderm). "Although the amount of their production from the teratoma is unclear, these factors have been reported to circulate in wt serum on the order of ng/mL (Prl2c, resistin, insulin growth factor 2, angiopoietin, C1qtnf3, Postn, IGFBPs, PPBP), and pg/mL (colony-stimulating factor 1)." (PMID 33888706, 2021).
ZIKV infections (1 paper, 2021). "Three of the differentially expressed proteins, i.e., Fibrinogen Alpha, Platelet Factor 4 Variant 1, and Pro-Platelet Basic Protein, predicted Zika virus infection at a ∼70% true-positive and 6% false-positive rate." (PMID 33582300, 2021). "Further, we used a machine learning approach to distinguish between the DENV and ZIKV infections based on protein expression profiles of the 13 differentially proteins and a subset of three proteins (FGA, PF4V1, PPBP)." (PMID 33582300, 2021).
tumor (99 papers, 2012 to 2026). "CXCL7, a chemokine also known as platelet-derived growth factor (PDGF) is encoded by the gene pro-platelet basic protein (PPBP) and has been implicated in various cancers due to its role in promoting tumor progression and metastasis." (PMID 40368902, 2025). "Another conclusion is that CXCL2 and PPBP may be associated with the inhibition of proliferation in the tumor, but only in some types of tumors." (PMID 37686093, 2023). "Although the DC-STAMP, PF4, and PPBP had links with tumor-associated immune response, the mechanisms of the synergistic effects of their interaction remain unclear." (PMID 35571050, 2022). "We observed that the expression levels of CCL15 and PPBP were downregulated in tumor tissues compared with the adjacent normal tissues." (PMID 36118890, 2022). "Notably, PPBP (also known as CXCL7) is a critical chemokine ligand that plays a critical role in promoting tumor proliferation through the CXCL7/CXCR1/2 signaling pathway." (PMID 35711675, 2022). "Using data from the HPA database, we found immunohistochemical images of five prognostic signature genes in normal and tumor tissues, including three upregulated genes (ANKLE1, PPP1R27, and AMH) and two downregulated genes (FLRT3 and PPBP)." (PMID 35676660, 2022). "In addition, PF4 and PPBP may function as tumor suppressors in cirrhotic HCC, meanwhile, CCL19 may act as a protective factor in non-cirrhotic HCC, while miRNAs regulate mechanisms still unclear, further experimental trials are still need to be launched in the future." (PMID 31346321, 2019). "The GFP/PPBP enrichment ratio was relatively stable over the first four EVHB-Chip in series, indicating that tumor EVs were captured with relatively high specificity." (PMID 29330365, 2018). "CAFs contribute to ECM production by secreting CXCL16 and enhancing MMP expression, which increases tumor stiffness and alters ECM structure.The binding of PF4/CXCL4 and PPBP/CXCL7 to CXCL12, mediated by G protein-coupled receptors, promotes EMT and the expression of chemokines and cytokines." (PMID 40038745, 2025). "As predicted, disruption of the FGL2/PPBP paracrine loop through FGL2 knockout and anti-PPBP antibody binding significantly suppresses the tumorigenic effects of FGL2 and prolongs survival in tumour-bearing mice." (PMID 36555253, 2022). "The results of necroptosis influences on the tumor immune microenvironment showed that significantly up-regulated expression levels of chemokines existed in Clusters B and C, such as CCL11, CCR1, CXCL10, and PPBP (upper part)." (PMID 35911707, 2022). "The bone marrow-derived multipotent mesenchymal stromal cells, under the influence of interleukin-6 (IL6) and chemokine (C-X-C motif) ligand-7 (CXCL7; also known as the pro-platelet basic protein), reportedly are capable of enriching the population of BCSCs in the tumor." (PMID 32883003, 2020).
cancer (49 papers, 2008 to 2025). A tumor composed of atypical neoplastic, often pleomorphic cells that invade other tissues. "Platelet markers that alter significantly in the presence of cancer have been identified as beta-2-microglobulin (B2M), pro-platelet basic protein (PPBP), thymosin beta 4 X-Linked (TMSB4X), and platelet factor 4 (PF4)." (PMID 35096878, 2021). "PPBP may be the ligand most associated with angiogenesis across the largest number of cancer types (17 out of 30)." (PMID 37686093, 2023). "In this regard, the correlation between PPBP expression and the count of endothelial cells in different types of cancer has been investigated." (PMID 37686093, 2023). "In our current study, the expression levels of CCL15 and CXCL7 (PPBP) were decreased in cancer tissues compared with the adjacent normal tissues." (PMID 36118890, 2022). "Unbiased analyses identified cancer-elaborated CXCL1/PPBP, potent myeloid cell chemoattractants that drive inflammation and metastasis via CXCR1/CXCR2 on host cells, as the transcriptional targets of IL-1β-fostered KRAS-IKKα addiction." (PMID 29445180, 2018). "When a combination of DNA, PPBP and PADI4 was considered, a unit increase in log DNA, log PPBP or log PADI4 was associated with a six-, five- and two-fold increase in cancer risk, respectively." (PMID 23468981, 2013). "The expression levels of CXCL12, THBS1, PPBP, GZMB, CD74, and UNC93B1 were higher in the cancer group than in the normal group." (PMID 36211454, 2022).
infection (29 papers, 2014 to 2025). The state of being infected such as from the introduction of a foreign agent such as serum, vaccine, antigenic substance or organism. "Among these genes, several encode chemokines (IL8, CXCL1, CXCL10, CXCL11, CXCL9, PF4, PPBP), a family of small proteins that play important roles in the immune system through leukocyte recruitment, cell communication and cell activation during infection." (PMID 26791855, 2016). "It has been reported that PF4 and PPBP belonged to the CXC chemokine family and played roles in platelet activation, platelet degranulation, immune response to infection, activation of neutrophils and monocytes, and tumorigenesis." (PMID 35571050, 2022). "In contrast, the expression of some inflammation-inducing factors (PPBP, MARCO) was consistently down-regulated in the middle and late stages of infection." (PMID 36338035, 2022). "Meanwhile, anti-inflammatory factors such as TNFAIP3, NFKBIA, NFKBIZ, SOCS1, SOCS3, and IL-10 were elevated, with the reverse trends for the inflammation-inducing genes PPBP and MARCO at 38 hpi, suggesting that the pro- and anti-inflammatory responses might coexist in PAMs during YC-2020 infection." (PMID 36338035, 2022).
infectious disease (2 papers, 2024 to 2025). A disorder directly resulting from the presence and activity of a microbial, viral, or parasitic agent in humans. "In addition, reports also suggest that PPBP is specifically expressed in various infectious diseases." (PMID 39372399, 2024).
inflammation (2 papers, 2021 to 2023). Aberrant reaction of the microcirculation characterized by movement of fluid and leukocytes from the blood into extravascular tissues. "Higher levels of Matrix metallopeptidase (MMP-12), C-X-C motif chemokine ligand-8 (CXCL8), neutrophil elastase, azurocidin 1 (AZU-1), and pro-platelet basic protein (PPBP) were observed in the sputum of ex-smoking asthmatics, which are linked to neutrophilic inflammation." (PMID 37367073, 2023).
PPBP also shares sentences with these, for which no sentence is quoted: viral infection (9 papers); atherosclerosis (5); neurosyphilis (5); cholangiocarcinoma (4); lymph node metastasis (4); acute coronary syndrome (3); bacterial infection (3); coronary heart disease (3); diabetic nephropathy (3); systemic lupus erythematosus (3); antiphospholipid syndrome (2); autoimmune disease (2); cardiovascular disease (2); cervical cancer (2); E. coli infection (2); endometriosis (2); familial hypercholesterolemia (2); hematologic malignancies (2); influenza (2); liver cancer (2); lung injury (2); lung squamous cell carcinoma (2); malaria (2); myelodysplastic syndrome (2); myocardial infarction (2); Nephroblastoma (2); Thrombocytopenia (2); acute disseminated encephalomyelitis (1); Acute hepatitis (1); acute kidney injury (1).
A further 74 diseases each share a sentence with PPBP in 1 paper.